SHH (sonic hedgehog signaling molecule)
Diseases named in the same sentence as SHH in open-access papers (continued):
Sharing a sentence is not in itself a finding about the gene and the disease.
pancreatic cancer (continued). "We found that pancreatic cancer cells secreted more Sonic hedgehog protein (SHH) under hypoxia by upregulating its expression and efficiency of secretion in a HIF-1-dependent manner." (PMID 29535824, 2018). "Our results showing that pancreatic cancer cells secreted more SHH under hypoxic conditions by expressing more SHH in a HIF-1-dependent manner are consistent with a previous report." (PMID 29535824, 2018). "We revealed that pancreatic cancer cells, when exposed to hypoxic conditions, secreted more SHH by enhancing the efficiency of secretion as well as the expression of SHH in a HIF-1-dependent manner." (PMID 29535824, 2018). "We also found that the SHH proteins secreted from hypoxic pancreatic cancer cells promoted the growth of fibroblasts by stimulating their Sonic hedgehog signaling pathway." (PMID 29535824, 2018). "Next, we investigated the possibility that SHH proteins secreted from pancreatic cancer cells activate the Sonic hedgehog pathway in the cancer cells themselves, which in turn would further increase the growth of fibroblasts via paracrine signaling." (PMID 29535824, 2018). "Here, we report that the commercial SHH inhibitor GDC-0449 reverses fibroblast-induced resistance to doxorubicin in Smoothened (SMO)-positive pancreatic cancer cells by downregulating SHH signaling proteins." (PMID 29042665, 2017). "Recently, several independent studies also reported that SHH signaling restrained pancreatic cancer progression." (PMID 29042665, 2017). "The interaction between CAFs and pancreatic cancer cells abnormally activates sonic hedgehog (SHH) signaling and facilitates tumor growth, metastasis, and drug resistance." (PMID 29042665, 2017). "Another key feature of pancreatic cancer is the abnormal activation of SHH signaling, which occurs in 70% of patients." (PMID 29042665, 2017). "The development of desmoplasia in the pancreatic tumor has been reported to be mediated through the activation of the Hh signaling pathway by the stroma-derived SHH." (PMID 28383487, 2017). "In conclusion, our study provides a novel and potential treatment paradigm for fibroblast-enriched pancreatic cancer using the combination of nano-Dox and SHH signaling inhibitor GDC-0449." (PMID 29042665, 2017). "Pancreatic tumor cells produce sonic hedgehog (SHH), which induces desmoplasia in a paracrine mechanism and supports pancreatic tumorigenesis." (PMID 28383487, 2017). "In order to confirm the expression of Hh signaling components, we performed immunofluorescence staining of pancreatic cancer cell lines with anti-SHH or anti-GLI1 antibodies." (PMID 27349387, 2016). "Cancer stem cells play important roles in cancer initiation and progression and the cancer stem cell markers aldehyde-1 dehydrogenase (ALDH-1) and sonic hedgehog (SHH) are therapeutic targets of pancreatic cancer." (PMID 27281617, 2016). "Pancreatic tumor cells express increasing amounts of SHH as they progress towards fully established PDAC, however, they are unresponsive to the ligand themselves." (PMID 25884700, 2015). "In this study, we demonstrated that activated SHH and inactivated Wnt signaling in irradiated tumor cells play a crucial role in the repopulation of colon cancer and pancreatic cancer cells." (PMID 25713298, 2015). "SHH pathway is an important signaling system that can activate the characteristic desmoplastic reaction present in the microenvironment of pancreatic tumors." (PMID 25935754, 2015). "In this study, the role of Wnt pathway in tumor repopulation and its relationship with SHH signaling pathway was investigated in colon cancer and pancreatic cancer cells." (PMID 25713298, 2015). "Upregulation of the FOXA1 gene in pancreatic cancer and basal cell carcinoma, due to the transcriptional regulation by the Sonic Hedgehog (SHH) pathway, has also been documented." (PMID 24944681, 2014).
pancreatic cancer (continued). "Several clinical trials have been initiated as a result of this and are recruiting patients to investigate the mechanism and treatment effect of pharmacological SHH-inhibitors in pancreatic cancer patients." (PMID 24084722, 2013). "In a separate genome-wide association study, common variants in the SHH, BTRC and HHIP genes have been associated with the risk of pancreatic cancer." (PMID 23826113, 2013). "Inhibition of SHH signaling also prolongs survival time of mice genetically pre-disposed to pancreatic cancer." (PMID 23762282, 2013). "The role of sonic hedgehog (SHH) in epithelial mesenchymal transition (EMT) of pancreatic cancer (PC) is known, however, its mechanism is unclear." (PMID 22900095, 2012). "Because SHH promotes tumor development predominantly through Gli1, we sought to understand its mechanism by identifying Gli1 targets in pancreatic cancer cells." (PMID 22900095, 2012). "Activity of the pro-inflammatory nuclear factor-κB (NF-κB) induces expression of Sonic Hedgehog (SHH) by pancreatic cancer cells and stromal cells, leading to activation of the Hedgehog pathway." (PMID 24213498, 2012). "The elevation of GLI1 and GLI2 in holoclones suggests higher activity of Hedgehog signaling, which was consistent with the higher level of SHH expression in CD44+CD24+ESA+ cancer stem cells isolated from human primary pancreatic cancer specimens." (PMID 21826251, 2011). "We first measured the expression of various components of SHH pathway in human pancreatic cancer AsPC-1, PANC-1, and MIA-PaCa-2 cell lines and pancreatic CSCs by RT-PCR." (PMID 22087285, 2011). "Single nucleotide polymorphisms (SNPs) in ABO, sonic hedgehog (SHH), telomerase reverse transcriptase (TERT), nuclear receptor subfamily 5, group A, member 2 (NR5A2) were found to be associated with pancreatic cancer risk." (PMID 22125638, 2011). "SHH plays a key role as a morphogenic factor and is related to the formation of various malignancies, including pancreatic cancer." (PMID 22125638, 2011). "Several single nucleotide polymorphisms (SNPs) in the gene regions of ABO, sonic hedgehog (SHH), telomerase reverse transcriptase (TERT), nuclear receptor subfamily 5, group A, member 2 (NR5A2) were found to be associated with pancreatic cancer risk." (PMID 22125638, 2011). "Quercetin could inhibit the growth, migration, and invasion and induced apoptosis of pancreatic cancer cells by antagonizing SHH and TGF-β/Smad signaling pathways." (PMID 39946409, 2025). "Furthermore, SHH overexpression is observed in pancreatic cancer precursor lesions (PanIN) and invasive carcinoma." (PMID 39087024, 2024). "In pancreatic cancer, the SHH pathway may also contribute to promotion perineural invasion and mediating metastasis with inhibition of the SHH pathway leading to reduced metastasis and lymphangiogenesis." (PMID 36428556, 2022). "In the inducible KRAS pancreatic cancer mouse model (Ptf1-Cre; Rosa26-rtTa; TetO-KrasG12D), it has been described that pancreatic tumor cells regulate PSCs non-cell autonomously by secreting factors including Sonic hedgehog (SHH)." (PMID 35159011, 2022). "Pancreatic cancer cells could activate the SHH signaling pathway which increased the expression of CGRP and TRPV1 in the dorsal root ganglion in a concentration- and time-dependent manner, resulting in the pain of pancreatic cancer." (PMID 35132349, 2022). "In 70% of pancreatic cancer tissue, overexpression of SHH suggests that Hedgehog signaling may be responsible for pancreatic cancer." (PMID 33670230, 2021). "A high expression of SHH enhances the size and metastasis of primary pancreatic tumors." (PMID 31979397, 2020). "One hypothesis has been proposed, claiming that the pancreatic epithelia secretes SHH that is essential in establishing and regulating the pancreatic tumor microenvironment in promoting cancer progression." (PMID 31979397, 2020).
pancreatic cancer (continued). "Studies indicated sonic hedgehog (SHH) ligand was conducive to occurrence of desmoplasia, and paracrine hedgehog (HH) signaling played a central role in tumorigenic communication between tumor cells and fibroblasts in the stroma in pancreatic cancer." (PMID 32587480, 2020). "SHH significantly affects both microenvironment and tumor progression, and is a potential target to suppress the desmoplastic and metastatic processes involved in pancreatic cancer." (PMID 31979397, 2020). "Aberrant SHH expression occurs in the early stages and during the progression of pancreatic cancer." (PMID 31979397, 2020). "One hypothesis has been proposed that states that the behavior of mesenchymal and endothelial cells is affected by SHH, which is secreted from pancreatic cancer in a paracrine manner." (PMID 31979397, 2020). "In addition, the SHH pathway induces epithelial-to-mesenchymal transition in gastric tumors, pancreatic cancer, and breast cancer." (PMID 31744214, 2019). "Previous work identified SHH as a mediator of the desmoplastic response in pancreatic cancer and suggested that the stroma may serve as a barrier to delivery of therapeutic compounds." (PMID 31744214, 2019). "Quercetin can suppress miR-21 to alleviate TGF-β-induced fibrosis and activate the JNK pathway to induce apoptosis in KRAS-mutant colorectal cancer cells and also could inhibit the SHH pathway to regulate pancreatic cancer stem cell characteristics." (PMID 31019539, 2019). "To examine whether the amount of SHH proteins secreted from cancer cells is increased under hypoxic conditions, we cultured pancreatic cancer cells, MIA PaCa-2, under normoxic or hypoxic conditions, and harvested culture media for Western blot analysis." (PMID 29535824, 2018). "We revealed that pancreatic cancer cells secrete more SHH under hypoxic conditions by increasing the efficiency of secretion as well as expression of SHH in a HIF-1-dependent manner, and promote the growth of fibroblast cells by stimulating the hedgehog signaling pathway in a paracrine manner." (PMID 29535824, 2018). "Thus, pancreatic cancer cells express SHH to activate GLI1 in stroma to create a tumor-supportive microenvironment." (PMID 30060755, 2018). "SHH secreted by pancreatic cancer cells could activate the hedgehog pathway and introduce a desmoplastic reaction in fibroblasts." (PMID 25811359, 2015). "We have shown previously that sphere cultures of pancreatic cancer cells enrich for cancer stem cells, and that combined targeting of the Sonic Hedgehog (SHH) and mTOR pathways may offer a new therapeutic option." (PMID 23825539, 2013). "Here we verify in four distinct primary pancreatic cancer cell lines derived from patient tumors that cancer stem cell-enriched sphere cultures indeed show marked overexpression of SHH and the Hedgehog target genes GLI-1 and GLI-2, as well as increased mTOR pathway activity." (PMID 23825539, 2013). "Furthermore, SHH pathway is highly activated in pancreatic cancer stem cells and plays an important role in maintaining stemness." (PMID 23762282, 2013). "SHH is excluded from the developing pancreas as well as the mature organ, but is upregulated in chronic pancreatitis, early pancreatic intraepithelial neoplasia (PanIN) lesions, and invasive pancreatic cancer (PC)." (PMID 22900095, 2012). "Furthermore, expression of SHH promotes proliferation, invasion, and metastasis of pancreatic cancer cells." (PMID 24213498, 2012). "Recent evidence indicates that SHH signaling pathway at the level of Gli genes has a critical role in normal pancreas development and there is mounting evidence that dysregulated SHH signaling plays some role in pancreatic cancer." (PMID 22087285, 2011).
pancreatic cancer (continued). "Activation of the SHH signaling cascade consistently induces Gli family transcription factors (Gli1 and Gli2), hence both Gli genes mRNA, expressed in pancreatic cancer cell lines and CSCs, stating potential involvement of SHH signaling in human pancreatic carcinogenesis." (PMID 22087285, 2011). "The data demonstrate that the components of SHH signaling pathway, including the ligand (Shh), the signaling molecules (Patched-1, Patched-2 and Smoothened) and effectors (Gli1, and Gli2) are expressed in human pancreatic cancer cell lines and pancreatic CSCs." (PMID 22087285, 2011). "Therefore, targeting cancer stem cells by SHH pathway could improve the outcomes of pancreatic cancer patients." (PMID 31979397, 2020). "Therefore, ABCG2-high pancreatic CSCs might be well targeted by 5-ALA PDT using an ABCG2 inhibitor, and this approach could be another way to target SHH signaling-activated pancreatic cancer cells." (PMID 31083682, 2019). "In pancreatic cancer development, ectopic mutant KRASG12D expression directly induced SHH transcription, suggesting that SHH is a downstream effector of oncogenic KRAS signaling." (PMID 41550359, 2026). "The reactivation of developmental genes such as WNT, SHH, and NOTCH occurs in certain pancreatic tumors." (PMID 39087024, 2024). "VASH2 increased the expression of ZEB1/2 in pancreatic tumors through activation of the SHH pathway, which both facilitated the EMT process and increased the resistance of pancreatic tumors to gemcitabine chemotherapy." (PMID 37821528, 2023). "At the same time, miR-409 directly targets The Sonic Hedgehog (SHH) and regulates apoptosis and autophagy through the SHH/GLI/MGMT pathway, thus mediating the resistance of pancreatic cancer to gemcitabine." (PMID 35965522, 2022). "It is revealed that through the sHH signal pathway, EIF5A regulated the proliferation of pancreatic cancer." (PMID 34234848, 2021). "Gli1 is a target of the Sonic Hedgehog (SHH) signaling pathway and is activated in pancreatic CAF, thus promoting pancreatic cancer progression." (PMID 34944807, 2021). "SHH/SMO inhibitors have been shown to inhibit the CSCs of some cancers, including pancreatic cancer (ALDH+ cells), colon cancer (CD133+ cells), breast cancer (CD44 +CD24− cells) and gastric cancer (CD44+ cells)." (PMID 32962123, 2020). "Hypoxia has been shown to increase HH pathway activation through the upregulation of SHH, Smoothened (SMO), and GLI1 transcription in a ligand-independent manner, leading to enhanced invasiveness of pancreatic cancer." (PMID 32707920, 2020). "Expression of SHH/GLI1 was found to be negatively correlated with E-cadherin in oral squamous cell carcinoma and pancreatic cancer patients." (PMID 31036836, 2019). "In pancreas cancer mouse models, IPI-926, a SHh inhibitor, resulted in increased gemcitabine delivery by depleting stromal tissue and increasing vascular density." (PMID 29891787, 2018). "Three typical cell lines of pancreatic cancer (PANC 1, MIA PaCa-2, and Capan-1) and one subline established in our laboratory (Capan-1 M9, see 3.2) showed positive staining with anti-SHH and anti-GLI1 antibodies." (PMID 27349387, 2016). "Researchers have observed aberrant expression of SHH in PDAC tumors as well as PanIN lesions, suggesting that upregulation of SHH expression contributes to pancreatic cancer initiation, development, and progression." (PMID 24325450, 2013). "SIBI strongly inhibits gene expression of SHH and downstream target genes such as GLI2 in primary pancreatic cancer cells in vitro." (PMID 23825539, 2013). "Our results highlight the critical role of SHH signaling in human pancreatic CSCs and the possibility of targeting Gli1 and Gli2 activator functions using GDC-0449 in pancreatic cancer stem cells." (PMID 22087285, 2011). "SHH and downstream components of the HH pathway have been shown to be upregulated in precursor lesions and primary pancreatic tumors, but not in the normal pancreas." (PMID 32707920, 2020).
pancreatic cancer (continued). "Hypoxia increased the expression of SHH in a HIF-1α-dependent manner, and its overexpression activated HH signaling and collagen Ι fibronectin formation, inducing desmoplasia and enhancing tumor aggressiveness in pancreatic cancer." (PMID 32587480, 2020). "It was discovered in the inducible oncogenic KRAS (Kirsten Rat Sarcoma) mouse model (Ptf1-Cre; Rosa26-rtTa; TetO-KrasG12D) in which pancreatic tumor cells regulate PSCs non-cell-autonomously by secreting factors including SHH protein." (PMID 33333727, 2020). "HIF-1α stimulates SHH expression in fibroblasts and cardiomyoblasts and SMO in pancreatic cancer, which suggests that, in situ, hypoxia could also induce SHH signaling in WJ-MSC." (PMID 28962669, 2017). "On the other hand up regulation of SHH, STK36, ERK12, RAS and down regulation of SUFU were co-occurring in Pancreatic cancer cell line, hence in our second simulation (Simulation 2), we considered all these co-occurrence as initial states to provide biologically realistic predictions." (PMID 23935937, 2013). "SHH expression was ~46 times higher in CD44+CD24+ESA+ xenografted pancreatic tumor cells than in normal pancreatic epithelial cells, compared to a 4-fold increase of SHH expression in unsorted pancreatic cancer xenograft cells." (PMID 24213498, 2012). "This included elements of the Hedgehog signaling pathway (SHH, GAS1), semaphorin signaling (SEMA3A, PLXNA1, PLXNB2, PLXND1, PLXNA2, FARP1, FARP2) and also axon guidance pathways (ROBO1, SLIT1, SLIT3 and SLITRK2), all notable for their involvement in pancreatic cancer progression and metastasis." (PMID 36429078, 2022). "In pancreatic tumors, PSCs can become myofibroblast-like and express α-SMA upon activation by growth factors (TGF-β and PDGF), inflammatory cytokines (TNF-α, IL-1, IL-6, IL-8, IL-10, etc.), as well as other factors such as EMMPRIM, ET-1, Angiotensin II, SHH, and further enrich the CAF pool." (PMID 34646829, 2021). "If stromal cells respond distinctly to SHH and IHH ligands, then IHH may play a more prominent role in angiogenesis in LAD than SHH due to the lower potency of IHH analogous to the diminished pathway response of Gas1−/−;Boc−/− fibroblasts in pancreatic cancer." (PMID 32108165, 2020). "Besides that, sonic hedgehog (SHH)/GLI1 expression induced a significant upregulation of expression level of S100A4, a member of the S100 gene family and a key EMT molecular marker in pancreatic cancer, while E-cadherin was markedly reduced." (PMID 31547193, 2019). "However, the inhibition of SHH secretion in the pancreatic tumors failed to provide clinical benefit to the therapy of pancreatic cancer; it, rather, led to increased tumor metastasis." (PMID 28383487, 2017). "During hypoxia, HIF-1α accumulation could introduce SHH rather than GLI activity in human pancreatic cancer cell lines." (PMID 25811359, 2015). "Since hypoxia simultaneously induces tumor cell EMT, invasion and Hh signaling activation without affecting SHH expression, we hypothesized that hypoxia contributes to increased pancreatic cancer cell EMT and invasion through a SMO-dependent manner Hh signaling." (PMID 23786654, 2013). "Taken together, we found that elevated GLI1 and GLI2, but not the ligands SHH and IHH, is required for the acquired gemcitabine resistance in pancreatic cancer both in cultured cells and in mice." (PMID 30382189, 2019). "According to the report, autocrine SHH-Ptch-SMO signaling is not required for cancer progression and alternative mechanisms keeping the expression of GLI target genes exist in pancreatic cancer cells." (PMID 27349387, 2016).